MYD88 (MYD88 innate immune signal transduction adaptor)
Diseases named in the same sentence as MYD88 in open-access papers (continued):
Sharing a sentence is not in itself a finding about the gene and the disease.
infection (continued). "MyD88, TLR2, and TLR4 regulated miRNA expression, such as let-7e, during the course of infection." (PMID 30555476, 2018). "RRV-T48A534V infection results in upregulation of RIG-I, MyD88, and IRF7 expression." (PMID 30131356, 2018). "Given our previous observation that the signaling molecule Myd88 is required for full clearance of a CEA10 strain, we hypothesized that Myd88 is involved in neutrophil recruitment to the site of infection after spore germination." (PMID 30071103, 2018). "By detecting extracellular T. cruzi through TLR2 and TLR4 at the moment of the infection, or intracellular T. cruzi through TLR9 and TLR7, the cardiomyocytes should activate the MyD88 pathway and induce CCL5 that will focus the recruitment of cytotoxic CD8+ T cells towards the infected cell." (PMID 30067739, 2018). "Here we show that infection of plasmacytoid dendritic cells (pDCs) with a recombinant virus lacking SH expression (rhMPV-ΔSH) enhanced the secretion of type I interferons (IFNs), which required TLR7 and MyD88 expression." (PMID 29789500, 2018). "myd88-/- larvae are more susceptible to CEA10, but not Af293, infection compared to wild-type controls, consistent with the idea that Myd88-mediated immune activation is required specifically for the response to CEA10." (PMID 30071103, 2018). "More important, the MyD88 gene transcription levels at the heart of tamoxifen-treated Mer+MyD88flox+/+ and Mer-/-MyD88flox+/- mice were not different after infection, despite the different basal MyD88 expression of uninfected mice." (PMID 30067739, 2018). "Collectively, in the absence of MyD88, a persistent infection induces hypergammaglobulinemia and autoantibody development driven by the aberrant activation of myeloid cells and BAFF secretion." (PMID 29973931, 2018). "Thus, presently, no consensus exists about the relative contribution of different receptors upstream MyD88 necessary for sustaining a robust Th1 response and contributing to CD4+ T cell memory formation in a model of infection." (PMID 28895840, 2017). "Nevertheless, in MyD88-/- primary fibroblasts, robust NF-κB activation was revealed upon infection with the EPEC nleB nleC nleE mutant, but not with the escV mutant." (PMID 28671993, 2017). "Furthermore, MyD88−/− and TLR9−/− C57BL/6 mice produced significantly less IFN-γ following infection with T. brucei brucei, coinciding with impaired parasite clearance and reduced survival." (PMID 28936213, 2017). "To examine if TLR7/8/MyD88 signaling affects intracellular Mav growth we next quantified Mav-CFP intensities across infected macrophages at the single cell level 4 hours and 3 days post infection." (PMID 28806745, 2017). "Mice lacking TLR12, the TLR-induced adaptor proteins MyD88 or UNC93B1 and the inflammasome proteins NLRP3 or ASC all exhibit a high susceptibility to Toxoplasma infection during the early stage of the infection due to an impaired innate immune response." (PMID 28701773, 2017). "Together, this suggests that under the conditions of our animal facility, the enhanced resistance of the IEC-MyDON mice is a direct consequence of functional MyD88 signaling in IEC upon infection, and not due to prior adaptations during the steady state." (PMID 28520792, 2017). "Myeloid differentiation primary response (MyD88) is a key signaling molecule necessary for Toll-like receptor (TLR) and interleukin-1 receptor (IL-1R)-mediated immune defense and has been shown to be necessary for corneal defense during infection." (PMID 28796783, 2017). "To examine whether MyD88 mediates inflammasome activation via regulation of autophagy, we first determined whether IOE infection could trigger formation of autophagosomes, which entails the recruitment of cytosolic Atg8/LC3 to the phagophore." (PMID 29049365, 2017).
infection (continued). "In our scratch infection model, following 24 hours of PA challenge, MyD88-/- mice had very little evidence of corneal infiltrates, or no clinical signs of infection, indicating a lack of inflammatory cell recruitment." (PMID 28796783, 2017). "In the current study, we sought to visualize and isolate bacteria from uninjured MyD88-/- corneas, in order to quantify penetrating bacteria without a scratch injury and evaluate clinical signs of infection in the knockout animals." (PMID 28796783, 2017). "To define the inflammasome complexes that contribute to IL-1β secretion following infection with virulent IOE and regulated by MyD88, we further analyzed mRNA expression of several inflammasome complexes (NLRP3, NLRC4, AIM2) in the liver tissues of WT and MyD88-/- mice on day 7 p.i with IOE." (PMID 29049365, 2017). "Furthermore, our group discovered that this immune response is mainly localized in the TG with the important role of the MyD88 adapter molecule along with IFN-γ and iNOS during infection." (PMID 28222752, 2017). "In contrast, MyD88-/- corneas had very little to no corneal opacities, or no clinical signs of infection, indicating a lack of inflammatory cell infiltration (0.5±0.0 clinical grading score, p<0.01 compared to WT, p<0.05 compared to IL-1R-/-)." (PMID 28796783, 2017). "MyD88 signaling in CD11c+ cells therefore may affect both recruitment and activation of ILC3 in response to the infection." (PMID 28520792, 2017). "Our experiments demonstrated that IEC-specific MyD88 reconstitution did not affect IL-22 production from ILC3 upon infection, indicating that the enhanced expression of RegIIIγ is not exclusively dependent on ILC3 activation." (PMID 28520792, 2017). "AIM2 levels did not change significantly with IOE infection, and were similar between WT and MyD88-/- mice." (PMID 29049365, 2017). "To confirm a functional role for MyD88 in Mav-induced responses we next assessed secretion of inflammatory cytokines 4 hours to 3 days post infection of macrophages treated with siRNA to MyD88 or non-targeted control (NTC)." (PMID 28806745, 2017). "Considering the important role of MyD88 in the TLR/IL-1R signalling pathway, the present study successfully constructed and developed a lentivirus-mediated MyD88 gene interference vector using RNAi, which showed good infection and interference effects." (PMID 27707937, 2016). "A recent study demonstrated that infection of monocyte-derived macrophages with a low-passage clinical strain of HCMV resulted in the upregulation of several TLRs, including TLR5, and expression of NF-κB via the MyD88 signaling pathway." (PMID 27182601, 2016). "For MyD88-dependent TLR signaling, the level of IRF7 remained unchanged throughout 24 hrs of infection in HT-29 cells, which might be affected negatively in RD cells as well, since IRF7 decreased in quantity early after infection." (PMID 27007979, 2016). "Infection resulted in potent activation of PKR that was dependent on TLR4 and MyD88 signalling." (PMID 27021640, 2016). "Myd88 and Tlr2 ablation produced pronounced effects over the development of a specific Th1 response, based on the classical IL-12/IFN-γ axis, during the course of the infection." (PMID 27377650, 2016). "In contrast, it has been found that Myd88 is not required for the initial recruitment of macrophages in a local hindbrain infection model, indicating that mycobacteria have evolved mechanisms to avoid TLR/Myd88-mediated defenses." (PMID 26324465, 2016). "To assess possible mechanisms of MyD88/TRIF/MAVS-independent resistance to RSV, we looked for indicators of antiviral activity and measured levels of IFN-γ and granzyme B in the airways (BAL fluid) at different time points after infection." (PMID 26688048, 2015). "In a second scenario, MyD88- and CARD9-coupled signals may act in distinct cellular compartments in the lung within the same time phase post-infection (p.i.)to induce chemokines and coordinate innate immune responses." (PMID 25621893, 2015).
infection (continued). "Likewise, LPS-binding protein (LBP) and myeloid differentiation primary response 88 (MYD88), also involved in TLR4 signaling, were significantly up-regulated after infection." (PMID 26018580, 2015). "At 48 hours after infection with D39, neutrophil counts in lungs had declined strongly in WT mice and were not different from those in Myd88-/- mice." (PMID 25700108, 2015). "Infection with a virus or tissue damage induced by a toxin similarly led to an increase in polyreactive antibodies in MyD88+/+, but not MyD88−/− mice." (PMID 26463758, 2015). "Indeed, under conditions of infection with a moderate MCMV dose, below the LD50 of BALB/c MyD88-/- mice, control of viral replication was significantly less efficient in these animals than in the three other mouse strains examined." (PMID 25954804, 2015). "Cellular localization of Hm-MyD88 in the absence of infection was further investigated in neurons and microglia by immunofluorescence and confocal microscopy analyses." (PMID 25880897, 2015). "This is consistent with the data showing that many MyD88-dependent genes are not suppressed during infection and suggests the bacteria only partially blocks activation of this important inflammatory transcription complex." (PMID 26510639, 2015). "Interestingly, WT DCs transferred into MyD88-/-, IL-12p40-/- or TNFR-I-/- recipients were also unable to migrate efficiently to DLN after BCG footpad infection." (PMID 26440518, 2015). "Unlike blood-stage infection, intravenous inoculation of PbA (clone 15cy1) sporozoites has absolute dependence on MyD88-dependent TLR2/4 pathway to develop ECM." (PMID 25157202, 2014). "Together, these data indicate that endothelial cell MyD88 has no role in antibacterial defense or in lung or distant organ injury after infection with Klebsiella via the airways." (PMID 25254554, 2014). "By 5 hours post-infection, bacterial survival was reduced to statistically similar levels in WT and FAK−/− macrophages, which may be the result of up-regulated MyD88-dependent inflammatory signaling occurring in both cell types." (PMID 24901456, 2014). "In addition, MVA infection of human macrophages triggers type I IFN and pro-inflammatory cytokines and chemokines via a TLR2/TLR6/MyD88 and MDA5/MAVS-dependent pathways." (PMID 24743339, 2014). "The infections were carried out in wild-type mice and in mice lacking MyD88, a protein required for signaling by the Toll-like receptors." (PMID 25010669, 2014). "This clearly demonstrates that MyD88 and TLR9 deficient mice have impaired immune response generation after infection with L.guyanensis, regardless of the presence of LRV virions." (PMID 24801628, 2014). "The btpB gene is present in Brucella and encodes a protein with a TIR-domain, and it inhibits innate immune response probably by binding to MyD88, restricting the TLR signaling and therefore, it contributes to the control of inflammation and establishment of infection." (PMID 25259715, 2014). "Except for CCL7, there was no upregulation of mRNA expression of chemokines after infection in both MyD88−/− and MyD88+/+ mice." (PMID 23374751, 2013). "In fact, the modulation of Sca-1 is a common denominator between several infection models, even present in the absence of MyD88 or interferon type I signaling." (PMID 23762028, 2013). "Macrophages isolated from the NLRP3−/− and caspase-1−/− mice failed to kill amastigotes and exhibited an infection index that was even higher than that observed in MyD88−/− macrophages." (PMID 24098823, 2013). "Recognition by innate immune receptors was required for SOCS3 expression, since Socs3 mRNA levels after infection were reduced in the Toll-like receptor adaptor molecule MyD88−/− BMM and BMM incubated with a NF-κB inhibitor but not in Irf3−/− BMM." (PMID 23853585, 2013). "Thirteen days after infection, a higher parasite burden was observed but there was no histological change in the liver, heart, lungs and small intestine of MyD88−/− and MyD88+/+ mice." (PMID 23374751, 2013).
infection (continued). "While in this study we did not evaluated the role of MyD88 in hMPV primary and secondary infection, our results indicate that TLR4 is not necessary to protect against viral challenge." (PMID 24205331, 2013). "An investigation into a role for MyD88 in macrophage activation or Th2 immunity during exposure to live infection is lacking." (PMID 22884360, 2013). "We tested this possibility in MyD88−/− mice, which unlike wild type animals, succumb to infection with C. rodentium." (PMID 23372726, 2013). "While no major effects on known targets of the MyD88-Traf6 pathway were observed, apolipoprotein-mediated lipid transport emerged as a novel infection-inducible pathway under control of miR-146a/b." (PMID 24112639, 2013). "In contrast, MyD88 is essential for antigen specific IgG production late in infection, but is not required for IgM generation over the course of infection." (PMID 22973560, 2012). "TLRs/MyD88 was required for inflammasome assembly after infection [vaccinia virus (TLR2/6), Candida albicans (TLR2), Vibrio (MyD88)] and stimulation with DAMPs [biglycan (TLR2/4)], environmental particles [alkane particles (TLR2)] or fungal components [zymosan and mannan (TLR2)]." (PMID 22295065, 2012). "This maturation is dependent of MyD88 adapter molecule and does not require infection as heat killed Brucella induce a similar phenomenon." (PMID 22479178, 2012). "Therefore, MyD88-dependent signal(s) appear responsible, in part, for IFN-γ, IL-6, and CXCL1 expression during late infection, although the mechanism(s) involved for targeting these factors remain to be identified." (PMID 22879997, 2012). "Since RSV activates TLR signaling (via TLR2 and TLR4) during infection, we next investigated whether TLR/MyD88 pathway is required for IL-1β secretion during RSV infection." (PMID 22295065, 2012). "Arginase-1 expression was significantly increased in MyD88 KO mice at day 14 following infection but not earlier." (PMID 22879997, 2012). "Our first observation is that infection by amastigotes from G strain did not activate signal pathway dependent on Myd88 nor reliant on Nod2 receptor." (PMID 22509418, 2012). "The transcriptional levels of MyD88, IRAK-1, and TRAF-6 were significantly increased in mice infected with either P. yoelii 17XL or 17XNL compared to control mice at one, three and five days post-infection." (PMID 22463100, 2012). "Upon infection of macrophages, F. novicida is initially recognized by TLR2 at the plasma membrane and in the phagosome, leading to the induction of a proinflammatory response dependent upon MyD88 and NF-κB." (PMID 21698237, 2011). "Upon infection, L. monocytogenes-derived lipoteichonic acids and lipoproteins are recognised by membrane-bound TLR2 receptors which transmit their signals via MyD88." (PMID 22114673, 2011). "As suggested by previous transcriptional profiling experiments, we confirmed that Myd88−/−and Rip2−/−macrophages, which are defective in TLR and Nod1/Nod2 signaling, respectively, strongly upregulated Il23a and Gem following infection with wildtype L. pneumophila." (PMID 21390206, 2011). "The observed low level of MyD88 transcripts expression in both PBMC and U87-MG cells might be due to the non-infection normal status of cells used in our experiments." (PMID 23492674, 2011). "Although the expression of IL-1R or MyD88 by recruited BM-derived cells had no impact on the outcome of the infection, IL-1R/Myd88 signaling by resident cells, at the site of infection, controlled the outcome of infection." (PMID 21857913, 2011). "High level IL-12p40 production in ΔROP16 infection was dependent on the host cell adaptor molecule MyD88, but surprisingly was independent of any previously recognized T. gondii triggered pathway linking to MyD88 (TLR2, TLR4, TLR9, TLR11, IL-1ß and IL-18)." (PMID 21931552, 2011).
infection (continued). "One unexpected finding was that elevated chemokine expression in MyD88 KO animals at 24 h post-infection did not translate into enhanced immune cell recruitment." (PMID 21496301, 2011). "MyD88 KO mice were exquisitely sensitive to intracerebral C. koseri, with the majority of animals succumbing to infection within 24-36 h following bacterial exposure (data not shown)." (PMID 21496301, 2011). "However, in the case of RABV it appears that MyD88-dependent signaling, and thus TLR-7, is dispensable for IFN-α/ß production following infection." (PMID 20661430, 2010). "infection seems to be managed in a MyD88-independent fashion, TLR2 and MyD88 are important for proinflammatory cytokine and type 1 IFN secretion as well as for the control of pulmonary MHV-68 loads following infection with a high dose of virus." (PMID 21060793, 2010). "To test whether activation of NFκB, a major transcription factor downstream of MyD88, is required for the elimination of Mp by BMM, we treated BMM cultures with an inhibitor of NFκB activation for 1 hour prior to infection with EYFP-Mp." (PMID 21203444, 2010). "The negative impact of DENV-ADE infection on the TLR-dependent pathway was strongly supported by gene array screening which revealed that both MyD88-dependent and –independent signaling molecules were down regulated during DENV-ADE infection." (PMID 21200427, 2010). "Much to our surprise, the MyD88/TRIF null mice, which are devoid of all TLR functions and show impaired production of pro-inflammatory cytokines when infected with T. gondii, were consistently more resistant to infection than the 3d mice." (PMID 20865117, 2010). "In order to determine if TLR-3 and MyD88 signaling might have an impact on type I IFN production, supernatant from infected BMDCs was collected at various times post infection, and a VSV-sensitivity assay was performed." (PMID 20661430, 2010). "The results suggest that a host response involving Tlr4 and Myd88 leads to TcpC dependent kidney pathology after CFT073 infection and that hosts lacking Tlr4 or the adaptor are protected from such tissue damage." (PMID 20886104, 2010). "NF-κB and IRF7 transcript levels, which are both MYD88 and TRIF dependent, were significantly increased after ΔTcpC infection compared to CFT073 (p<0.01), suggesting that also TRIF-dependent signaling, might be inhibited by TcpC." (PMID 20886104, 2010). "Within siNC treated groups, both MyD88 and TRAF6 were consistently down-regulated with SE challenge (-2.34 - fold at 1 h and -2.37 - fold at 4 h, post-infection for MyD88, and -1.60 - fold at 1 h and -1.45 - fold at 4 h post-infection for TRAF6)." (PMID 21637513, 2009). "Our studies demonstrate that TLR2 signaling via MyD88 plays an important role in innate immune responses to F. tularensis infection in vivo regardless of the route of infection and regardless of the subspecies of F. tularensis." (PMID 19936231, 2009). "Survival of TLR2−/− and MyD88−/− mice, however, was significantly reduced compared to B6 mice, regardless of the route of infection or the subspecies of F. tularensis." (PMID 19936231, 2009). "Nevertheless, with NF-kB 1 inhibition, MyD88 was significantly (p = 0.0047) up-regulated 1.28 - fold at 1 h post-infection, whereas no significant change was found in TRAF6 expression." (PMID 21637513, 2009). "Blockade of the IL-10 receptor or the absence of MyD88 during primary infection restored protective immunity." (PMID 19730694, 2009). "Our data are in line with other studies showing the crucial role of MyD88 in host defense against infection with both gram-positive and gram-negative bacteria." (PMID 18946505, 2008). "MyD88 KO mice tended to have more lung injury compared to WT mice, however lung inflammation scores were not significantly different at 72 hours after infection between both mice strains (data not shown)." (PMID 18946505, 2008).